HIF1A (hypoxia inducible factor 1 subunit alpha)
Diseases named in the same sentence as HIF1A in open-access papers (continued):
Sharing a sentence is not in itself a finding about the gene and the disease.
tumor (continued). "The establishment of a hypoxic tumor cell culture condition was confirmed by measuring the increased expression of HIF-1α using Western blot analysis, and increased luminescence using a hypoxia-responsive luciferase activity assay." (PMID 30558324, 2018). "The first one is observed at the very early stage of tumor growth, just before the angiogenic switch (as a result of HIF1α increase and VEGF production)." (PMID 30412628, 2018). "HIF3A expression was evenly distributed in the different tumor zones, while HIF1A, HIF2A, and ARNT expressions were enriched in the perinecrotic zones and/or in blood vessels of the tumor (Online Resource 9)." (PMID 29149419, 2018). "We show that MOLP8/R, like other tumor cells, overexpressing HIF1α, have an increased resistance to the immune system." (PMID 29882856, 2018). "ALPPS induced: tumor progression on deportalized lobe and metastases; expression of hepatic vasculogenic factors (HIF1-α and VEGF); and a dramatic increase of Kupffer cells (KCs) and tumor-associated macrophages (TAMs)." (PMID 29795479, 2018). "Cytoplasmic VEGFR1 and nuclear HIF1α were expressed in about 50% (80/161) and 37% (56/153) of tumor cells and, according to the median value > 0 for both markers." (PMID 29716631, 2018). "Considering the hypoxic nature of the tumour microenvironment, overexpression of HIF-1α is an established fact." (PMID 29914529, 2018). "In general HIF1a is commonly used to indicate hypoxia in the tumor tissue and VEGF is continuously expressed throughout the tumor life cycle." (PMID 30123419, 2018). "Taking together, we surmise that nimbolide induces CS in P-glycoprotein-overexpressing cells by targeting PTEN and modulating tumor cellular metabolic elements (HIF1α, FoxO1, c- MYC and ROS)." (PMID 30515268, 2018). "In human cancers, overexpression of HIF-1A in tumor tissue compared with normal tissue has been revealed in many human cancers." (PMID 30315244, 2018). "The adaptation of tumor cells to the hypoxic condition is regulated by the hypoxia inducible factor-1α (HIF1α)." (PMID 29882856, 2018). "In tumor cells, high glucose levels are known to promote HIF-1α expression under both normoxic and hypoxic conditions." (PMID 30455857, 2018). "We also reported that miR-3662 acted as a tumor suppressor in HCC by directly targeting HIF-1α and ulteriorly inhibiting tumor growth and metabolic reprogramming." (PMID 29748591, 2018). "Our previous study and two other studies conducted at the same time suggest that miR-153 inhibits endothelial cell activity and tumor angiogenesis through downregulating the hypoxia-induced HIF1α/VEGFA pathway." (PMID 29959560, 2018). "The target genes of HIF-1α encourage an aggressive phenotype, promoting tumor growth, invasion and metastasis." (PMID 30455857, 2018). "PKM2 also enhances vascular endothelial growth factor (VEGF)-A-dependent tumor angiogenesis by HIF1α activation." (PMID 30257458, 2018). "Aberrant VEGF production in a tumor environment is induced through activation of hypoxia-inducible factor 1α (HIF-1α) mostly under hypoxia and results in the formation of disorganized and leaky tumor vessels." (PMID 30214642, 2018). "Because hypoxia and aneuploidy are both barriers to tumor progression, the ability of Hif-1α to promote cell survival following chromosome missegregation raises the possibility that aneuploidy tolerance coevolves with adaptation to hypoxia." (PMID 30332653, 2018). "For instance, HIF-1α can directly promote tumor growth via binding to the promoters of the genes involved in glycolysis, such as glucose transporters (i.e., GLUT1, GLUT3) or enzymes (i.e., LDH-A)." (PMID 30151352, 2018).
tumor (continued). "It is plausible that HO-1 overexpression, and subsequent increase in HO-1 activity, stabilize HIF-1α in tumor cells, driving downstream effects on pro-survival signaling." (PMID 29311669, 2018). "HIF1-α depletion in endothelial cells was shown to suppress the migration of tumour cells through endothelial cells, but HIF2-α depletion was shown to stimulate metastatic spread." (PMID 29362402, 2018). "The mechanism for regulating the function and differentiation of MDSCs in the tumor microenvironment involves the transcriptional factor HIF-1α." (PMID 30619850, 2018). "This leads to an upregulation of pro-angiogenic HIF-1α target genes, an increase in tumor angiogenesis, and enhanced tumor development." (PMID 29628507, 2018). "HIF-1α is an oxygen-dependent transcription factor, and a hypoxic environment promotes the high expression of HIF-1α gene in tumor cells and plays an important role in tumorigenesis, development, invasion, metastasis, and apoptosis." (PMID 29531823, 2018). "GLUT-1 and HIF-1α proteins were strongly stained in LoVo tumor tissues compared with HT29 tumor tissues (55.1 ± 2.85 vs. 32.94 ± 7.62 and 29.14 ± 2.63 vs. 23.13 ± 1.43, respectively, P < 0.05) measured by immunohistochemistry and expressed as mean density." (PMID 30546057, 2018). "The combined treatment also reduced the HIF-1α protein levels and collagen deposition in tumor tissue." (PMID 30367042, 2018). "Accumulated studies confirm that hypoxia can strongly induce HIF-1α-dependent PD-L1 expression on tumor cells, macrophages, and dendritic cells." (PMID 30061885, 2018). "In the hypoxic tumor stroma, up-regulated HIF-1α and STAT1 expression in TAMs triggers NO secretion and induces arginase activity respectively to induce T-cell apoptosis and halt their expansion." (PMID 30619850, 2018). "Exposure of tumor cells to hypoxia induces stabilization of hypoxia-inducible factor 1α (HIF-1α), which dimerizes with HIF-1β to form a transcription factor complex." (PMID 29164272, 2018). "One of the principal actions of HIF-1α is to shift tumor metabolism from oxidative phosphorylation to anaerobic glycolysis." (PMID 30111297, 2018). "As expected from those observations, HIF-1α was highly expressed in several solid tumors, and forced suppression of HIF-1α impaired tumor angiogenesis, growth and metastasis." (PMID 29558908, 2018). "In mammalian cells, WWOX ablation is inversely correlated with increased levels and activity of hypoxia-inducible factor 1α (HIF1α-enhancing cell transformation and tumor growth." (PMID 29724996, 2018). "A, one way analysis with outlier box plot of necrosis, HIF-1α in perinecrotic or in vital central tumor regions, P-RPS6, P-PRAS40 and Iba1 in tumors of patients treated with nimotuzumab (nimo) or placebo (cont)." (PMID 30129426, 2018). "HIF-1α promotes tumor growth and metastases by promoting angiogenesis and regulating host cell metabolism." (PMID 30405048, 2018). "In saline and LI groups, the tumor slides showed a deep brown color, demonstrating the high expression of HIF-1α in the tumors." (PMID 29461122, 2018). "Within tumours CA IX is mainly distributed in perinecrotic areas, likely due to its acknowledged regulation by hypoxia through hypoxia-inducible factor 1 α (HIF-1α)." (PMID 29967776, 2018). "Intratumoral injection of Fuco-MnO2-NPs also alleviated tumor hypoxia in vivo, as supported by decreased HIF-1α expression in xenografted tumor tissues." (PMID 30558324, 2018). "Many lines evidence validated the proposal that the hypoxic microenvironment regulated by HIF1α in tumor cells is responsible for their aggressiveness, their resistance to chemotherapy, and morphologic changes, in order to escape the hostile conditions." (PMID 29882856, 2018). "High HIF-1α expression was localized to the nuclei and cytoplasm in 69.05% (87/126) of the resected tumor tissue samples." (PMID 29515112, 2018).
tumor (continued). "Reprogramming glucose flux is considered as a major factor to shape the tumor microenvironment via increase of HIF-1α levels in rapidly growing tumor cells within hypoxic regions." (PMID 30061885, 2018). "HIF-1α has been reported to regulate the function and differentiation of MDSCs within the hypoxic tumor microenvironment." (PMID 30423905, 2018). "MSC has an anti-vascular effect, and can increase the antitumor effect of irinotecan through the inhibition of HIF1α, which leads to decreased microvessel density, lowered tumor interstitial pressure, and increased pericyte coverage of blood vessels." (PMID 30513765, 2018). "Since the IFN-α-induced HIF-1α expression plays a potential role in inflammatory tumor-environment, we next sought to determine possible tumor propensities offered by IFN-α in TME." (PMID 29587825, 2018). "The key transcription factor, HIF-1α, in the tumor microenvironment is also bidirectional in regulating Tregs." (PMID 30477520, 2018). "While HIF1α serves mainly as a tumor suppressor in kidney cancer, HIF2α stabilization, as a result of VHL loss, is sufficient and necessary in the promotion of kidney tumor growth." (PMID 29562667, 2018). "Radiotherapy reduced the expression of HOTAIR and HIF-1α in tumor tissues and HeLa cells or C33A cells." (PMID 30355300, 2018). "We also work on relieving the hypoxic of tumor by down-regulating the expression of hypoxia inducible factor-1α (HIF-1α) and its downstream vascular endothelial growth factor (VEGF), which was generally believed to be highly expressed in hypoxia." (PMID 29461122, 2018). "Some tumor biomarker expression pattern changes after neoadjuvant chemoradiation do support the concepts of tumor reoxygenation or altered HIF-1α signaling." (PMID 29681762, 2018). "IHC analysis of the SK-RC-52 tumors with different size showed the presence of HIF1α in all nuclei from tumor cells but also reflects necrosis and a high heterogeneity of CAIX expression across the tumor." (PMID 30487460, 2018). "PHD2 inactivation led to HIF-1α stabilization and increased tumor growth in human colon carcinoma (HCT116), colorectal carcinoma (HT29 and RKO), and pancreatic carcinoma (SU.86.86) models." (PMID 29896451, 2018). "STAT3 is induced in tumor cells under hypoxic conditions, which triggers tumor cell production of hypoxia inducible factor 1 alpha (HIF-1α) and VEGF; VEGF then acts on endothelial cells to promote cell proliferation and angiogenesis." (PMID 30200630, 2018). "Hypoxia and HIF-1α stabilization regulates the MDSCs within the tumor enhancing their role as T-cell suppressors." (PMID 29896451, 2018). "The results indicated that the percentage of HIF-1α positive cells in tumor tissue was an independent factor for TMR value (p < 0.01)." (PMID 30246018, 2018). "In the same way, it has been previously demonstrated that there is a connection between the abrogation of HIF-1α activity and reduced tumor cell viability and migration, reducing consequently also the metastatic potential." (PMID 30013951, 2018). "Differential sensitivity of the three tumor lines to exercise was paralleled by effects on intratumoral Ki-67, Hif1-α, and metabolic programming." (PMID 29254140, 2017). "Hypoxia is the initial inducer of malignant transformation and tumor metastasis, and HIF-1α plays an important role in regulating tumor angiogenesis." (PMID 29282026, 2017). "Pereira and her colleagues found that ER stress potentiated HIF1α activity to transactivate VEGF expression in tumor cells." (PMID 29100382, 2017). "A significant increase in the expression of ETS‐1 and HIF‐1α was found in the tumor sample from LPA‐treated of mice." (PMID 28236660, 2017). "Similar accumulation of HIF-1α was also observed in patient tumor derived xenografts treated with Minnelide." (PMID 28801636, 2017).
tumor (continued). "Although one would expect that induction of energy stress by metformin, through complex I inhibition, would likely induce HIF1α, studies demonstrate suppression of HIF1α by metformin, which is suggested to contribute to the anti-tumor action of the drug." (PMID 28915708, 2017). "Western blotting of 12 HNSCC tumours consistently showed a significantly positive correlation of GATA3 with HIF-1α and GATA3 with SLC2A1, a well-known HIF-1 target (Pearson’s correlation coefficient=0.65 and 0.64, respectively, P<0.05)." (PMID 28263977, 2017). "FBP1 was shown to exhibit dual tumor-suppressive functions, in gluconeogenesis as well as a HIF1A inhibitor." (PMID 29285300, 2017). "Downregulation of miR-1 significantly increased HIF-1α expression, resulting in enhancement of tumor glycolysis and tumor growth." (PMID 28471448, 2017). "Although the inhibition of HIF-1α and IL-8 has been found to have a significant influence on tumor angiogenesis in animal studies, the effect thereof was restricted to specific hypoxic conditions." (PMID 28053598, 2017). "We found that CD133-expressing stem-cells had significantly higher mRNA expression levels of BECN1, BNIP3L, MAPLC3B, CAIX and HIF1A than CD133-negative tumor cells (p < 0.05)." (PMID 28445132, 2017). "We examined the relationship of DNA lesions and HIF-1α expression with tumor invasion in intrahepatic cholangiocarcinoma patients." (PMID 28825631, 2017). "Our results demonstrated that expression of CA IX and HIF-1a in tumor tissues of mice was reduced by bacteria treatment via IHC and western blotting analysis." (PMID 29206859, 2017). "Next, we interrogated the potential involvement of STK33 in HIF-1α regulation by HSP90 in hypoxic tumor cells." (PMID 29100402, 2017). "This indicated that even though Minnelide was inhibiting the hypoxic state of the tumor, it was resulting in accumulation of HIF1A." (PMID 28801636, 2017). "HIF-1α has been found to be highly expressed in a variety of malignant tumors and precancerous lesions, indicating that it is closely related with tumor angiogenesis, invasion and metastasis." (PMID 29267502, 2017). "pylori-infected SIRT3-overexpressing cells, indicating that SIRT3 is an effector molecule responsible for negative regulation of ROS, HIF-1α, and tumor growth induced by H. pylori CagA." (PMID 29108235, 2017). "Again, tumours in HIF-1α KO mice had significantly lower volumes at day 14, despite a reduction in NK cell infiltration and a lower fraction of degranulating CD107A+ NK cells." (PMID 29150606, 2017). "Here, we show that either long-term (72 h) exposure to hypoxia (1% O2) or elevated expression of CHCHD4 in tumor cells in normoxia leads to perinuclear accumulation of mitochondria, which is dependent on the expression of HIF-1α." (PMID 28497026, 2017). "HIF-1α was one of the important transcription factors in tumor development and progression, contributed to cell survival, and activation of gene expression under hypoxic condition." (PMID 29026004, 2017). "Macroscopic inspection of tumours revealed severe tumour haemorrhage in isografts from HIF-1α KO mice, indicating an immature vascular phenotype with excessive leakage." (PMID 29150606, 2017). "RT‐induced elevations of both VEGF HIF‐1α are reported to confer radioprotection to tumour vasculature." (PMID 29084756, 2017). "Hypoxia inducible factor 1α (HIF-1α) is an important determinant of the switch to anaerobic metabolism in both normoxic and hypoxic tumor cells." (PMID 28619042, 2017). "HIF-1α inhibition altered tumor metabolism in mice exposed to a low oxygen environment (7% O2 for 3 h) but had minimal effect on tumors in air-breathing animals." (PMID 28619042, 2017). "Increased DLL4 expression was observed in EV-tumours treated with bevacizumab compared to control (VII versus I) as DLL4 is induced by hypoxia through HIF-1α." (PMID 28445154, 2017). "HIF-1α was generally activated in subcutaneous tumors, suggesting that the tumor cells suffered from hypoxia." (PMID 28052003, 2017).
tumor (continued). "Consistently, the average tumor weight in the DDP/si-HIF-1α group was significantly lower than those in the other groups." (PMID 28790395, 2017). "Although hif-1α is accumulated in the tumor microenvironment, it is probably a passive phenomenon and is not the main mechanism responsible for chronic or persistent hypoxia." (PMID 28705232, 2017). "It seems to have suppressed HIF-1α stability and activity in cancer cells, and to have synergistically inhibited tumor growth when combined with other chemotherapeutic agents." (PMID 27999195, 2017). "Insulin-like growth factor 1 (IGF1) plays a pivotal role in the progression of diverse malignancies, and has been shown to promote tumor angiogenesis by activating the HIF-1α/VEGF signaling pathway." (PMID 29212519, 2017). "In our previous study, we confirmed that miR-33a-5p functions as tumor suppressor mainly via directly binding HIF-1α 3’UTR." (PMID 29137372, 2017). "The overexpression of both HIF-1α and SEPT9_i1 has been correlated with tumor progression in numerous cancers." (PMID 28380438, 2017). "Previous studies have shown that HIF-1α is activated in the tumor tissues of mice fed a HFD, and has a role in the regulation of important features of angiogenesis." (PMID 28410190, 2017). "Last, immunohistochemical analysis demonstrated decreased NF-κB, STAT3, and HIF-1α expression levels in the tumor tissue treated with miR-302b." (PMID 28467773, 2017). "HPV-positive HNSCC cells show activation of the HIF pathway and adaptation to HIF-1α upregulation, representing potential therapeutic targets in this emerging tumor entity." (PMID 29163780, 2017). "Through negative regulation of HIF-1α, Parkin inhibits cancer metastasis, which is an important mechanism for Parkin in tumor suppression." (PMID 29180628, 2017). "In vitro studies showed that TWIST1 mRNA transcription is regulated by tumor hypoxia in a HIF-1α dependent way." (PMID 29165393, 2017). "Independent shRNA-mediated HIF-1α knockdown also decreased wound healing, cell migration, invasion, and tumor formation, showing that the STAT3/HIF-1 α signaling pathway is responsible for tumorigenesis in MPNST." (PMID 28825044, 2017). "Together, these results demonstrate that 64B triggers the energy sensor AMPK in tumor cells and downregulates mTORC1 signaling, leading to diminished HIF-1α protein synthesis, in effect disrupting the hypoxia-induced HIF-1 transcriptome." (PMID 29245898, 2017). "Its inactivation or mutation would cause HIF-1α/2α accumulation and activation, leading to vascular endothelial growth factor (VEGF) expression and tumor angiogenesis." (PMID 28404914, 2017). "The present study demonstrated that the HIF1α pathway and tumor metabolism are differentially regulated between HPV (+) and HPV (-) HNSCC cells." (PMID 28881665, 2017). "We found that deletion of HIF-1α in NK cells inhibited tumour growth despite impaired tumour cell killing." (PMID 29150606, 2017). "In summary, we show by T cell-specific gene deletion that HIF-1α is an essential regulator of T cell effector responses in the tumor microenvironment." (PMID 29136509, 2017). "In these GATA3 and HIF-1α double-positive tumours, we further categorized the distribution of positive staining into two types: invasive front and diffuse." (PMID 28263977, 2017). "Hypoxic tumor regions (indicated by HIF1a) showed reduced E-Cadherin levels, but melatonin treatment visibly increased E-Cadherin localization at the cell membrane." (PMID 29212174, 2017). "Further studies are required to elucidate the relationship between Smad3 and HIF-1α, such as the effect of this interaction on HIF-1α stabilization, during tumor glycolysis and tumor progression." (PMID 28471448, 2017). "In contrast, HIF-1α expression was inhibited in YC-1- or YC-1 + GI-treated tumours, but apoptosis markers were more strongly induced by YC-1 + GI than YC-1." (PMID 28978999, 2017).